SLC16A1 (solute carrier family 16 member 1)
Diseases named in the same sentence as SLC16A1 in open-access papers (continued):
Sharing a sentence is not in itself a finding about the gene and the disease.
renal clear cell carcinoma (1 paper, 2024). "For instance, in renal clear cell carcinoma, targeting and blocking SLC16A1 can downregulate lactate flux, thereby inhibiting the proliferation and invasion capabilities of the cancer." (PMID 38911368, 2024). "However, at the protein expression level, significant differential expression of SLC16A1 was only observed in certain urological tumors 17, 18, such as renal clear cell carcinoma 19, 20, which is consistent with previous research findings." (PMID 38911368, 2024).
squamous cell carcinoma (1 paper, 2015). A carcinoma arising from squamous epithelial cells. "We selected two proteins consistently overexpressed in squamous cell carcinoma in all studies, MCT1 (SLC16A1) and GLUT1 (SLC2A1), for further investigation." (PMID 26539827, 2015).
Stomach adenocarcinoma (1 paper, 2025). "In the public database, the correlation analysis revealed that HNRNPC expression was positively correlated to the MCT1 (SLC16A1 gene) level in STAD (Stomach adenocarcinoma) samples." (PMID 40977716, 2025).
Stroke (1 paper, 2026). Sudden impairment of blood flow to a part of the brain due to occlusion or rupture of an artery to the brain. "In contrast, SLC16A1, SIRT3, PFKP, and TKT were inversely associated with stroke risk, suggesting a potential protective role." (PMID 41877258, 2026).
triple-negative breast carcinoma (1 paper, 2022). An invasive breast carcinoma which is negative for expression of estrogen receptor (ER), progesterone receptor (PR), and human epidermal growth factor receptor 2 (HER2). "In triple negative breast cancer, miR-342-3p was found to directly reduce SLC16A1; as miR-342-3p was downregulated due to a lack of estrogen receptor, SLC16A1 levels were shown to be increased." (PMID 35755805, 2022).
urinary tract tumors (1 paper, 2021). "However, SLC16A1 was significantly overexpressed in tumor tissues of most other cancers (ESCA, GBM, HNSC, etc.)(P<0.05), and this feature was more strongly present in urinary tract tumors (Kich, Kirc, Prad) (P<0.05)." (PMID 34631536, 2021).
tumor (117 papers, 2009 to 2026). "Immunohistochemical staining showed that decreased Ki67 expression was associated with reduced tumor growth via downregulation of circ-SLC16A1." (PMID 38539084, 2024). "Interestingly, this involves local production of ketone bodies by tumor-associated fibroblasts and the SLC16A1 (MCT1)-mediated influx of the ketone bodies in the tumor microenvironment into tumor cells for use in energy production." (PMID 40305364, 2025). "Recent studies showed that reverse Warburg metabolism creates a metabolic niche for stem cell-like properties, giving rise to chemoresistant- and tumor relapse-initiating cancer cells, which mainly accounts for the poor prognosis of cancer patients associated with tumoral SLC16A1 expression." (PMID 40508207, 2025). "The results showed that SLC16A1 could promote the occurrence and development of tumor by inducing MMRS mutation and up-regulating the activity of DNMTs." (PMID 34631536, 2021). "SLC7A11 mediates SLC16A1-driven tumor cell proliferation, ferroptosis resistance, and tumorigenesis." (PMID 42065048, 2026). "To further validate the tumor growth-promoting effect of SLC16A1 in vivo, we performed a xenograft experiment by subcutaneously injecting SLC16A1-knockdown cells and control cells into the right anterior axillary region of nude mice." (PMID 40302798, 2025). "Immunohistochemical analysis revealed a reciprocal expression of TMPRSS11B and BSG together with SLC16A1 in some areas of tumor tissues from PDAC patients." (PMID 40508207, 2025). "In vivo experiments further corroborated the pivotal role of SLC16A1 in promoting HNSCC tumor growth." (PMID 40302798, 2025). "The protein level of LDHA was relatively low and SLC16A1 was higher in tumor tissues than in controls." (PMID 40782248, 2025). "In tumor cells, SLC16A1 is highly expressed during the transport of L-lactate derived from glycolysis." (PMID 40782248, 2025). "Studies have shown that inhibiting or knocking down SLC16A1 in mixed cancer cell-fibroblast xenografts in mice can delay tumor growth." (PMID 40362379, 2025). "Conversely, a xenograft experiment using HN6 cells overexpressing SLC16A1 confirmed that overexpression of SLC16A1 enhanced the proliferation of tumor cells in vivo." (PMID 40302798, 2025). "The experimental outcomes revealed that mice injected with SLC16A1-knockdown cells exhibited significantly reduced tumor volumes and weights compared with those injected with control cells." (PMID 40302798, 2025). "Among them, SLC16A1 plays a crucial role in lactate transport, which is essential for tumor metabolism." (PMID 40362379, 2025). "The results showed that LDHA was downregulated and SLC16A1 was upregulated in LGG tumor tissues compared to normal tissues in TCGA dataset." (PMID 40782248, 2025). "The solute carrier family 16 member 1 (SLC16A1) gene demonstrates abnormally elevated expression levels in a variety of human malignant tumors, and it is pivotal in tumor initiation and progression." (PMID 40302798, 2025). "To bring our research closer to clinical application, we chose 5-FU for experimentation to verify the impact of SLC16A1 expression levels on tumor cell drug sensitivity." (PMID 38911368, 2024). "SLC16A1 encodes for monocarboxylate transporter 1 (MCT1), a lactate transporter that contributes to shaping an acidic tumor microenvironment." (PMID 39519080, 2024). "It was observed that SLC16A1 was expressed in almost all constituent cell types of the CCA tumor microenvironment." (PMID 38911368, 2024). "In our previous studies, we discovered that SLC16A1 plays a crucial role in driving the progression of tumor cells." (PMID 38911368, 2024). "Downregulation of circ-SLC16A1 inhibited tumor growth by reducing proliferation, lung metastasis, and lymphatic metastasis of NSCLC cells, and arrested the cell cycle in the G1 phase." (PMID 38539084, 2024).
tumor (continued). "Studies have observed that inhibiting or knocking down SLC16A1 in mixed cancer cell-fibroblast xenografts in mice can delay tumor growth." (PMID 38911368, 2024). "Lastly, using single-cell datasets (GSE138709) from TISCH, we studied the expression and distribution of SLC16A1 across different cell types in the tumor microenvironment of CCA at the single-cell level." (PMID 38911368, 2024). "Kaplan–Meier survival analysis found that high circ-SLC16A1 expression was negatively correlated with survival and positively correlated with lymphatic metastasis and tumor–node–metastasis (TNM) classification." (PMID 38539084, 2024). "A coculture of CAFs with PDAC cells revealed that most of the glucose was taken up by the tumor cells and that CAFs consumed lactate via the monocarboxylate transporter 1 (SLC16A1, SE = 2.8) to enhance proliferation through the TCA cycle." (PMID 38892190, 2024). "A mouse tumor xenograft model was employed to determine the roles of circ-SLC16A1 in NSCLC progression and metastasis in vivo." (PMID 38539084, 2024). "Considering that the mechanisms of action of SLC16A1 vary with tumor types in previous studies, future research needs to combine bioinformatics analysis to explore the mechanisms of SLC16A1 further." (PMID 38911368, 2024). "For instance, SLC16A1 can interact directly or indirectly with components of the NF-kB signaling pathway, facilitating the survival and metastatic activities of tumor cells." (PMID 38911368, 2024). "To further investigate this, we conducted in vitro and in vivo studies to assess the impact of SLC16A1 on tumor growth." (PMID 38911368, 2024). "Remarkably, studies have shown that microRNA is involved in the transcription regulation of SLC16A1. miR-342-3p specifically targets SLC16A1, which supports the alteration of lactate fluxes, thus disrupting tumor cell metabolic homeostasis." (PMID 35664312, 2022). "Recently, SLC16A1 has been shown to be upregulated in HNSCC tumour tissues compared to adjacent normal marginal tissues, emphasising its potential oncogenic role in cancer progression likely through the NF-κB pathway." (PMID 35327656, 2022). "CD147 functions as a chaperone of MCT1 (also known as SLC16A1) and its downregulation is known to be detrimental to proper lactate transport and tumour survival." (PMID 35723405, 2022). "The analysis showed that the expression of ACAT1, BDH1 and SLC16A1 was significantly higher in bone metastatic samples when compared with the primary tumor site (P = 0.0042, P = 0.0091, and P = 0.0006, respectively)." (PMID 34584218, 2021). "We also analyzed the normal samples in GTEX and tumor samples in TCGA and found that the high expression pattern of SLC16A1 was more obvious in urological cancers (ACC,KICH,Kirc,PRAD,TGCT)." (PMID 34631536, 2021). "The expression level of SLC16A1 in tumor tissues of BRCA, CHOL, COAD, UCEC and other cancer patients was lower than that in their corresponding paracancerous normal tissues (P<0.001)." (PMID 34631536, 2021). "SLC16A1 is necessary and sufficient for the uptake of the anti-cancer drug 3-bromopyruvate into tumor cells and its overexpression re-sensitizes 3-bromopyruvate-resistant cells to the drug in xenograft models." (PMID 34298852, 2021). "In contrast, expression levels of the related monocarboxylate transporter SLC16A1/MCT1 were similar in all tumour types." (PMID 22362593, 2012). "The expression levels of LDHA and SLC16A1 in LGG and control samples were extracted from TCGA and GTEx expression profile datasets, and the expression differences of LDHA and SLC16A1 in the tumor vs. normal groups were analyzed by R Wilcoxon test according to grading." (PMID 40782248, 2025). "The lactate-to-pyruvate ratio (Lac/Pyr) correlates strongly with HIF1α expression, linking metabolic activity to hypoxia and tumor volume, while also showing associations with lactate dehydrogenase A (LDHA) and monocarboxylate transporter 1 (SLC16A1/MCT1) expressions." (PMID 41515572, 2025).
tumor (continued). "In addition to its known promoting effect on lactate export through SLC16A1 and -A3 in highly glycolytic tumor cells, favoring Warburg metabolism and proliferation, it prevents lactate uptake by SLC16A1 in tumor cells, driving reverse Warburg metabolism." (PMID 40508207, 2025). "Thus, our findings indicate that high expression of SLC16A1 positively regulates HNSCC tumor growth." (PMID 40302798, 2025). "Notably, SLC16A1 exhibits high expression in various types of tumors, and it is considered to play an important role in the process of tumor metastasis 21-26." (PMID 40302798, 2025). "Furthermore, IHC analysis of the tumor tissues demonstrated a marked decrease in the expression of the cell proliferation marker Ki-67 in the SLC16A1-knockdown tumors." (PMID 40302798, 2025). "For example, SLC16A1 can interact directly or indirectly with components of the NF-κB signaling pathway, thereby enhancing the survival ability and metastatic potential of tumor cells." (PMID 40302798, 2025). "Previous studies have indicated that SLC16A1 may play a role in the remodeling of the tumor immune microenvironment by regulating lactate." (PMID 38911368, 2024). "Further immune infiltration analysis revealed a significant correlation between SLC16A1 and the infiltration levels of cells like neutrophils and macrophages in the tumor microenvironment, indicating SLC16A1's potential involvement in regulating the tumor immune microenvironment of CCA." (PMID 38911368, 2024). "Interestingly, SLC16A1's protein expression in OV varied between cohorts: it was lower in tumor tissues than in normal tissues in the JHU cohort, whereas it was higher in the PNNL cohort." (PMID 38911368, 2024). "H1833 cells were transfected with a lentivirus carrying circ-SLC16A1 to assess tumor formation." (PMID 38539084, 2024). "In addition, results from IHC staining demonstrated that compared to the control group, SLC16A1 Knockdown significantly reduced the number of Ki-67 positive cells in mouse tumor tissue and it also had a slight impact on the expression of Caspase-3." (PMID 38911368, 2024). "Additionally, blocking the lactate influx mediated by SLC16A1 in endothelial and osteoclast cells impairs tumor-induced angiogenesis and bone resorption, thereby inhibiting tumor progression." (PMID 38911368, 2024). "Overall, our results suggest that SLC16A1 may act as an oncogene, promoting tumor growth and invasion, thereby impacting the clinical outcomes of CCA patients." (PMID 38911368, 2024). "Furthermore, some SLC16s alter the anti-tumor functions of tumor-infiltrating lymphocytes including the T reg cells, which maintain their suppressive activity by SLC16A1 overexpression involved in the lactate uptake." (PMID 37397501, 2023). "High SLC16A1 expression was associated with cell cycle, PI3K-Akt and other signaling pathways, which may suggest that high SLC16A1 expression may be involved in tumor progression through regulation of the cell cycle." (PMID 34631536, 2021). "This also suggests that SLC16A1 is involved in tumor development from another perspective." (PMID 34631536, 2021). "SLC16A1 may promote tumor development by regulating the epigenetic process of urological cancer and demonstrated a great potential as a prognostic biomarker of urological cancer patients." (PMID 34631536, 2021). "Interestingly, in the present study, LDHA encoding lactate dehydrogenase A was downregulated in LGG tumor tissues, which may cause less lactate accumulation, leading to reduced growth and invasion of LGG, despite the MCT1 (SLC16A1) upregulation." (PMID 40782248, 2025). "Thus, the contribution of LDHA and MCT1 (SLC16A1) to tumor progression deserves attention." (PMID 40782248, 2025). "Therefore, we hypothesize that SLC16A1 might indirectly affect the sensitivity of tumor cells to anticancer drugs by regulating their metabolic pathways." (PMID 38911368, 2024).
tumor (continued). "Furthermore, CD147 represents the obligatory binding partner for several proteins involved in carcinogenesis, e.g., the monocarboxylate transporters (MCT) 1 and MCT4 (encoded by SLC16A1 and SLC16A3, respectively), which mediate the export of lactate from highly glycolytic tumor cells." (PMID 26384346, 2015). "Volcano plot analysis of differentially expressed genes showed that NDRG1 is markedly upregulated in tumor tissues, alongside several key metabolic genes, including LDHA, SLC16A1, PKM, HK1, and LDHB." (PMID 40539245, 2025). "Given that migration and invasion are pivotal characteristics of tumor development and progression, we conducted in vitro migration and invasion assays using HNSCC cell lines with varying levels of SLC16A1 expression." (PMID 40302798, 2025). "Slc16a1 (MCT1) knockout preserves peripheral Treg function but significantly impairs intratumoral Treg inhibitory function, restricting tumor growth." (PMID 41181157, 2025). "Integrated analysis of GTEx (normal, n = 171) and TCGA (tumor, n = 179) datasets revealed higher expression of CHST11, SLC16A1, RHOF, MAN1C1, SPRR1B, and ANO6 in tumors." (PMID 41346619, 2025). "The expression levels of LDHA and SLC16A1 in GSE15824 and GSE16011 of all tumor samples (grades I–IV) were also extracted." (PMID 40782248, 2025). "So, circ-SLC16A1 is identified as a mediator of multiple pro-oncogenic signaling pathways in NSCLC and can be targeted to suppress tumor progression." (PMID 38539084, 2024). "Among these monocarboxylate transporters, MCT1 (SLC16A1) and MCT4 (SLC16A3) displayed heterogeneous expression patterns across distinct tumor cell clusters." (PMID 38730450, 2024). "Further research addressing these issues will provide more insights into the role of SLC16A1 in the drug resistance mechanisms of CCA and its important role in tumor development and progression." (PMID 38911368, 2024). "Then, survival analysis indicates that a high expression of SLCA6A3, SLC16A1, and LDHA and a low expression of LDHB are recognized as a tumor progression promotor in some tumors." (PMID 37122693, 2023). "LAGs like SLC16A8, SLC16A1, and LDHB have a higher methylation ratio in tumor tissue than in normal tissue; a lower methylation ratio of SLC16A7 and SLC16A3 is noticed in that comparison." (PMID 37122693, 2023). "Cells absorb glucose via GLUT1(SLC2A1), hypoxic cells release lactate through MCT4(SLC16A4), while tumor cells and endothelial cells absorb lactate through MCT1(SLC16A1)." (PMID 37795453, 2023). "Using transgenic mouse models, we observed that SLC16A1 and SLC16A3 were both over‐expressed from normal mouse prostate to PIN lesions and medium and advanced PTEN‐null tumours." (PMID 25875424, 2015). "In vitro studies indicate that Merkel cell polyomavirus (MCV) oncogene expression enhances the transcription of glycolytic genes, such as the monocarboxylate transporter SLC16A1 (MCT1), thereby promoting aerobic glycolysis, which is characteristic of malignant and rapidly proliferating tumor cells." (PMID 41602751, 2026). "Also, silencing of circ-SLC16A1 inhibited proliferation of NSCLC cells and tumor growth, as well as migration and metastasis of NSCLC cells in lung and lymphatic tissues." (PMID 38539084, 2024). "Lactate shuttle, which is needed for establishment of a synergistic metabolism between glycolytic tumor cells and tumor cells relying on OXPHOS, is highly dependent on the activity of lactate transporters MCT1 and MCT4 (SLC16A1 solute carrier family 16, members 1 and 4)." (PMID 37376060, 2023). "For discrimination of the normal and tumour sampling zones, we were able to derive an effective gene-based classifying model for molecular abnormality based on a panel of eight genes (MMP1, MMP12, MYO1B, TNFRSF12A, WDR66, LAMC2, SLC16A1 and PLAU)." (PMID 35327656, 2022).